MMP9 (matrix metallopeptidase 9)
Diseases named in the same sentence as MMP9 in open-access papers (continued):
Sharing a sentence is not in itself a finding about the gene and the disease.
breast tumor (continued). "A reported 85 kDa pro-form of MMP9 in breast tumor cells, lacking complex carbohydrates, is also visible in our zymograms while control fibroblasts solely exhibit the 92 kDa pro-form band." (PMID 27588391, 2016). "For example, aberrant STAT3 signaling promotes breast tumor progression through deregulation of the expression of downstream target genes, which control proliferation (Bcl-2, Bcl-xL, survivin, cyclin D1, c-Myc, and Mcl-1), angiogenesis (Hif1α and VEGF), and EMT (vimentin, Twist, MMP-9, and MMP-7)." (PMID 36446524, 2023). "In this study, we report a fibronectin-targeting and MMP-9-activatable imaging probe (CREKA-GK8-QC) used for specific fluorescence imaging of breast tumors (including the primary malignancy and lung metastatic foci) and image-guided complete resection of breast tumors." (PMID 36978072, 2023). "Thus, the differential expression of MMP-13 in breast tumor progression may be regulated by a mechanism different from those for MMP-2 and MMP-9." (PMID 18373849, 2008). "Thus, MMP-13 may be independent of MMP-2 and MMP-9 as a marker as well as a regulator of breast tumor progression." (PMID 18373849, 2008). "No statistic correlation was observed between breast tumor tissue miR-21 expression levels and those of CCL-2, RANKL and MMP-9, probably due to the low number of samples." (PMID 36890825, 2023).
renal fibrosis (84 papers, 2012 to 2025). A final common manifestation of a wide variety of chronic kidney diseases characterized by glomerulosclerosis and tubulointerstitial fibrosis. "MMP-7 and MMP-9 are associated with a profibrotic effect and are protective against renal fibrosis after unilateral ureteral obstruction." (PMID 39033222, 2024). "Specifically, matrix metalloproteinases (MMPs), a family of zinc-containing endopeptidases, such as MMP2 and MMP9 have been linked to alterations of the tubular basement membrane, leading to renal fibrosis and tubular atrophy." (PMID 35045102, 2022). "Under fibrotic conditions, excessive secretion of extracellular matrix components (ECM), such as collagen I, α-SMA and MMP-9, promotes the pathological process of renal fibrosis, leading to metabolic syndrome-associated renal disease." (PMID 33819919, 2021). "MMP-2 and MMP-9 play various roles in the renal disease progression, contributing to loss of glomerular cell junctions, epithelial-to-mesenchymal transition, and increased renal fibrosis, accelerating the decline in renal function." (PMID 39123230, 2024). "MMP-9 is also associated with renal outcomes and renal fibrosis." (PMID 30942116, 2019). "A recent study showed that long-term low-grade inflammation, with sustained increased PTX3 levels, may underlie renal fibrosis in ESRD due to a MMP-9/TIMP-1 imbalance." (PMID 31316299, 2019). "In addition, it has been shown that reduced expression of MMP9 in the cytoplasm of normal tubular cells is associated with renal fibrosis, whereas MMP2 is associated with structural changes in the tubular basement membrane leading to tubular atrophy and fibrosis." (PMID 35045102, 2022). "MMP9 and MMP2 belong to the matrix metalloproteinase family and are closely associated with the process of hypertensive nephropathy and renal fibrosis." (PMID 40391375, 2025). "This study explores the expression of NONO in DN and its correlation with Matrix Metalloproteinase-9 (MMP-9, as an important regulator of fibrosis), renal fibrosis, and prognosis." (PMID 41163679, 2025). "MMP-9 inhibition has been shown to decrease neutrophil and other inflammatory cell infiltration and renal fibrosis." (PMID 40391375, 2025). "Persistent infiltration of specific neutrophils, such as Siglec-F+ or MMP-9+ neutrophils, is crucial for creating a pro-fibrotic microenvironment that facilitates the progressive renal fibrosis." (PMID 38770013, 2024). "Matrix metallopeptidase 9 (MMP-9) represents a pivotal enzyme within the matrix metalloproteinase family, playing a significant role in the progression of renal fibrosis." (PMID 38790620, 2024). "In further agreement, other studies confirmed that direct or indirect inhibition of MMP-9 activity by Hesperidin resulted in a decrease in renal fibrosis in obstructive nephropathy." (PMID 36547838, 2023). "Elevated HE4 inhibits the degradation of collagen I by inhibiting the activity of serine proteases (Prss23 and Prss35) and matrix metalloproteinases (MMP-2 and MMP-9) and accelerates the deposition of type I collagen in the kidneys, leading to renal fibrosis." (PMID 37753112, 2023). "Prior researches have proved that MMP-9 can control extracellular matrix (ECM) deprivation throughout renal fibrosis." (PMID 36547838, 2023). "In the current study, we found that DCI certainly enhanced the expression of PPAR-γ and MMP-9, decreased NF-κB activity, and reduced renal fibrosis in mice." (PMID 35439732, 2022). "ClC-5 expression inhibits immune cell infiltration and inflammatory cytokine release and ameliorates renal fibrosis by inhibiting NF-κB-mediated activation of MMP-9 pathway signaling." (PMID 36277193, 2022). "Other reports indicated that MSCs can protect against renal fibrosis caused by obstruction via downregulating STAT3 and upregulating STAT3-dependent MMP-9." (PMID 36422526, 2022).
renal fibrosis (continued). "In HK-2 cells, rhein inhibited high-glucose-induced EMT by inhibiting ILK expression and regulating the MMP-9/TIMP-1 ratio to relieve renal fibrosis." (PMID 36235108, 2022). "Elevated expression of MMP-9 and MMP-13 was reported to be associated with renal fibrosis in DN25,42,43." (PMID 36522378, 2022). "The data showed a significantly increased expression of MMP-9 and the decreased expressions of MMP-7 and MMP-13 were associated with UUO-induced renal fibrosis." (PMID 35754468, 2022). "MMP-9 is an essential matrix metalloproteinase involved in the process of renal fibrosis, which can be regulated in different levels, and finally, the endogenous MMP-9 inhibitor TIMP-1 inhibits the enzyme activity." (PMID 34594474, 2021). "It was previously reported that ECM alleviation was mediated mainly by MMPs, including matrilysins and collagenases, etc, especially MMP2 and MMP9, which are closely correlated with renal fibrosis." (PMID 33507617, 2021). "The ECM degradation is mainly catalysed by MMPs, including MMP2 and MMP9, which are related to renal fibrosis." (PMID 33507617, 2021). "Previous studies have shown that in the process of renal fibrosis, the expression of MMP-9 and TIMP-1 were both increased, which resulted in an imbalanced/decreased MMP-9/TIMP-1 ratio and led to reduced capacity of MMP-9 to degrade ECM." (PMID 34082748, 2021). "The implication of MMP2 and MMP9 in renal fibrosis is controversial as their expression/activity was reported to be both up- and downregulated depending on the stage of CKD." (PMID 34127702, 2021). "Previous studies have confirmed that matrix metalloproteinase-9 (MMP-9) can regulate extracellular matrix (ECM) degradation during renal fibrosis." (PMID 34082748, 2021). "In the experimental model of renal fibrosis, the expression of MMP-9 was found in mesangial cells, glomerular cells, epithelial cells and endothelial cells, fibroblasts, macrophages, and neutrophils." (PMID 34992536, 2021). "It was observed that MMP-9 contributes to the pathogenesis of renal fibrosis through macrophage recruitment and osteopontin cleavage." (PMID 32670438, 2020). "The current study showed that exercise training suppressed TGF-β, p-Smad2/3, CTGF, MMP2, and MMP9 expression to decrease renal fibrosis." (PMID 29461477, 2018). "A candidate marker of renal fibrosis is matrix metalloproteinase-9 (MMP-9), which was found to be elevated in the urine and plasma of CKD patients compared to controls." (PMID 30271792, 2018). "Specimens of forty-six patients were examined by immunohistochemical stain of MMP-9 in nephrectomized kidneys, and the association of renal expression of MMP-9 and renal fibrosis was determined." (PMID 23110201, 2012). "In other words, the process of renal fibrosis involves a decline of MMP-9 expression in normal tubular cytoplasm and an increased expression of MMP-9 in the tubular nuclei of atrophic renal tubules." (PMID 23110201, 2012). "In summary, our analysis of the spatial expression of MMP-9 in human nephrectomized specimens indicates a novel role for MMP-9 in renal fibrosis." (PMID 23110201, 2012). "Our results indicate that renal fibrosis is associated with a decline of MMP-9 expression in the cytoplasm of normal tubular cells and increased expression of MMP-9 in the nuclei of tubular atrophic renal tubules." (PMID 23110201, 2012). "EZP and EYP inhibited the gene expression of FN1 and MMP9 in a renal fibrosis cell model." (PMID 40417738, 2025). "Our investigation suggested that Chaga may mitigate renal fibrosis by modulating Mmp9 expression via its distinct molecular constituents, underscoring a potential therapeutic mechanism of action against renal fibrotic processes." (PMID 40160460, 2025). "To investigate whether SiNPs induce renal fibrosis, we determined the expression levels of MMP-9, MMP-2, TIMP-2, and TGF-β1 in kidney tissue using RT-qPCR." (PMID 38655071, 2024).
renal fibrosis (continued). "We found that hyperoxia exposure during nephrogenesis was associated with increased renal fibrosis markers in adulthood, including elevated TGF-β1 kidney expression, upregulation of MMP-7 and MMP-9 and downregulation of genes involved in the antifibrotic BMP signaling pathway." (PMID 39033222, 2024). "Inhibition of MMP-9 in the early phase of renal fibrosis and the late phase of nephropathy could decrease tubular cell pEMT." (PMID 38260142, 2023). "They established the pathogenesis of MMP-9’s influence to renal fibrosis via osteopontin cleavage." (PMID 36547838, 2023). "MMP9 is proposed to play a role in renal fibrosis and epithelial-to-mesenchymal transition." (PMID 37468493, 2023). "The ratio of MMP-9/TIMP-1 is considered as a potential indicator for evaluating renal fibrosis." (PMID 36235108, 2022). "Recently, it has been reported that dysregulated MMP-9 may relate to the pathogenesis of renal fibrosis." (PMID 34082748, 2021). "Among them, MMP-9 plays the most representative role in the progression of renal fibrosis." (PMID 34992536, 2021). "The contribution of MMP-9 in renal fibrosis was evaluated more extensively than MMP-2." (PMID 32670438, 2020). "Based on these findings, we speculate that inhibition of autophagy with 3-MA may decrease collagen formation and ECM protein deposition through regulating the activity of MMP2/MMP9, which results in alleviating hyperuricemic-related renal fibrosis." (PMID 32555189, 2020). "In a model of renal fibrosis, activation of STAT3 was associated with the up-regulation of MMP-9." (PMID 31557909, 2019). "Many groups found that increased activity of MMP9 may have an antifibrotic effect, and an MMP9 inhibitor has been used to construct some renal fibrosis models, while other groups found that MMP9 plays a pro-fibrosis role by promoting macrophage accumulation." (PMID 31130867, 2019). "The exact mechanism by which MMP-9 contributes to renal fibrosis still is a matter of debate." (PMID 30978213, 2019). "Altogether, our results suggested that IOs downregulated MMP-9 expression, which may be contributed to Col IV synthesis and renal fibrosis." (PMID 28662169, 2017). "A recent study showed that binding of HE4 to MMP2 and MMP9 in renal cells promotes renal fibrosis." (PMID 25362534, 2014). "Although the molecular basis of increased intranuclear MMP-9 expression in renal fibrosis is still unknown, these findings form a basis for further investigation of the role of MMP 9 in human renal injury." (PMID 23110201, 2012). "Based on these previous studies and because MMP-9 is associated with ECM accumulation and tubulointerstitial fibrosis, we examined the relationship between histological renal expression of MMP-9 and renal fibrosis, including glomerular and interstitial fibrosis." (PMID 23110201, 2012). "Similarly, MMP-9) plays a profibrotic role in renal fibrosis." (PMID 38655071, 2024). "Interestingly, the CXCL8 antagonist G31P has been shown to improve renal fibrosis by reducing ECM, which may be associated with improved expression of MMP-2 and MMP-9." (PMID 37287620, 2023). "Therefore, based on our results, we speculate hypothesize that DCI protects the kidney by enhancing the expression of PPAR-γ and possibly alleviating renal fibrosis through the NF-κB/ MMP-9 signalling pathway." (PMID 35439732, 2022). "However, MMP-2 and MMP-9 also play a role in the process of renal fibrosis." (PMID 34205319, 2021). "Indeed, DCN increases MMP-2 and MMP-9 levels, reduces extracellular matrix deposition, and attenuates fibrotic changes in animal models of many pathological conditions, including proliferative vitreoretinopathy, renal fibrosis, and spinal cord injury." (PMID 33918979, 2021). "Therefore, MMP2 appears to be more crucial in the development of renal fibrosis than MMP9." (PMID 28396839, 2017).
renal fibrosis (continued). "Thus, it may be suggested that NGAL is overexpressed to delay the progression of renal fibrosis in diabetic nephropathy, by preserving the enzymatic activity of MMP-9." (PMID 26904288, 2016). "Thus, we speculated that MMP2 and MMP9 play a role in the formation of polycystic kidney lesions and renal fibrosis in a different way from MMP1." (PMID 24595031, 2014). "EVs released by engineering MSCs mediate the transfer of miRNA-let7 to diseased kidneys and alleviate renal fibrosis by inhibiting fibrosis genes COL-4, MMP-9, α-smooth muscle actin (α-SMA), TGF-β 1, and their receptors." (PMID 40332144, 2025). "Fibronectin 1 (FN1) and matrix metalloproteinase 9 (MMP9) were the typical extracellular matrix (ECM) and pathological biomarkers of renal fibrosis." (PMID 40417738, 2025). "Several studies have shown that ROS accumulation promotes the expression of MMP2, and MMP9 participates in all stages of different forms of CKD, which is characterized by renal fibrosis." (PMID 38785272, 2024). "Through PPI network and molecular docking module analyses, CASP3, MMP9, ANXA5, and HSP90AA1 were identified as major pivotal gene targets in renal fibrosis." (PMID 37179298, 2023). "The renal fibrosis amelioration was confirmed by the reduction in mRNA levels of Acta2, Collagen I, Collagen III, Mmp2, and Mmp9 and the protein levels of ACTA2, fibronectin, and Collagen I in UI30/2wk Pfkfb3f/f/PostnMCM kidneys compared to PostnMCM kidneys." (PMID 37626891, 2023). "After 6 months, the treated group showed increased levels of MMP-2 and MMP-9, reduced levels of TIMP-1, TIMP-2, and TGF-β/Smad signalling, improved renal fibrosis and enhanced renal function." (PMID 37196129, 2023). "Network pharmacology analysis and experimental results suggest that diosmin ameliorates renal fibrosis by decreasing the expression of CASP3, ANXA5, MMP9, and HSP90AA1." (PMID 37179298, 2023). "Network pharmacology analysis and molecular docking technology were used to explore the potential mechanism of action of diosmin against renal fibrosis, and the key therapeutic targets of diosmin were identified as CASP3, MMP9, ANXA5, and HSP90AA1." (PMID 37179298, 2023). "In renal fibrosis, TGF-β-activated macrophages release MMP-9, which specifically degrades the tubular basement membrane, leading to tubular cell EMT and ultimately kidney fibrosis." (PMID 35897082, 2022). "By cleaving osteopontin, a macrophage chemoattractant, MMP-9 activates transforming growth factor-β (TGF-β), a cytokine that induces renal fibrosis." (PMID 34707724, 2021). "Since the increase in MMP-9 activity was more striking than that of MMP-2 in our present study, it was thus plausible that MMP-9 was more predominant than MMP-2 in driving renal fibrosis mediated by COM-MP secretome." (PMID 34381146, 2021). "As described ahead, the transfer of let-7c from MSC-EVs ameliorated renal fibrosis in UUO model through the downregulation of Col4a1, MMP-9, TGF-β1, and TGFBR1." (PMID 31979395, 2020). "The results of our study suggest increased synthesis and release of MMP-9 in patients with UPJO and the development of renal fibrosis." (PMID 32670438, 2020). "As described ahead, let-7c from MSC-EVs ameliorated renal fibrosis in UUO model with the downregulation of Col4a1, MMP-9, TGF-β1, and TGFBR1." (PMID 31979395, 2020). "The COL4A3−/−/ITGA2−/− double knockout Alport mouse model has delayed renal fibrosis compared with COL4A3−/−/ITGA2+/+ Alport mice, which express significantly higher levels of MMP2, MMP9, MMP12, and TIMP155." (PMID 29196624, 2017). "Also, our PCR array reveals that MMP9 but not TGF-β may be a major fibrotic factor for CLU deficiency-induced renal fibrosis." (PMID 27649757, 2016). "In addition, we also detected increased expression of renal fibrosis related proteins (α‐SMA, TGF‐β, CTGF, Col I, FN, and MMP9)." (PMID 37506140, 2023).
renal fibrosis (continued). "Moreover, the inhibition of matrix metalloproteinase (MMP)-9 and decreased expression of MMP-1 resulted in decreased histological evidence of renal fibrosis." (PMID 36176443, 2022). "In addition, MMP-9 expression is affected, and ECM degradation is reduced, promoting the process of renal fibrosis." (PMID 35439732, 2022). "In addition, upregulated MMP-9 and MMP-13, excessive collagen deposition in the glomerular and tubulointerstitial regions, and degradation of vascular elastin resulted to renal fibrosis in the Akita mice." (PMID 36522378, 2022). "Inhibition of MMP-9 activity can reduce macrophage recruitment and infiltration, prevent the EMT and reduce the degree of fibrosis, making MMP-9 a potential therapeutic target in renal fibrosis." (PMID 35897082, 2022). "TGF-β1 is known to drive renal fibrosis via down-stream Smad-dependent signaling and is involved in epithelial-mesenchymal transition and in the regulation of ECM turnover through the induction of pro-fibrotic molecules, including α-SMA, collagen 1 and MMP9." (PMID 33672316, 2021). "In this study, we show that the pan-DUB inhibitor PR-619 reduces expression of mesenchymal markers, deposition of ECM proteins, expression of MMP2 and MMP9, the degree of apoptosis, macrophage infiltration, and the TGF-β1 mRNA level, and attenuates renal fibrosis." (PMID 30114247, 2018). "Therefore, the core genes CASP3, ANXA5, MMP9, and HSP90AA1 may play key roles in the inhibition of the occurrence and development of renal fibrosis." (PMID 37179298, 2023). "Thus, we believed that except for the EMT process, the MMP-9-related signaling induced by CyPA/CD147 interactions also plays a vital role in the extracellular matrix deposition and degradation, and consequently renal fibrosis." (PMID 36203223, 2022). "Furthermore, MMP-2 and MMP-9 directly affect renal tubular cells, especially by impairing the cell-to-cell adhesion, leading to epithelial-to-mesenchymal transition (EMT), which contributes to renal fibrosis." (PMID 34402375, 2021). "In addition, high expression of MMP-9 can induce epithelial-mesenchymal transformation (EMT) in tubular cells, which may be another mechanism for inducing renal fibrosis." (PMID 34082748, 2021). "Therefore, baicalein may suppress hyperuricemia-induced renal fibrosis involving MMP-7 and MMP-9 signals." (PMID 28445133, 2017). "Therefore, we hypothesize that NONO may mediate ECM expression by regulating MMP-9 levels, thereby participating in renal fibrosis." (PMID 41163679, 2025). "Immunohistochemical and RT-PCR results showed increase of MMP9 and decrease of its tissue inhibitor TIMP-1, thereby leading to an enhanced ratio of MMP/TIMP and hence degradation of extracellular matrix (ECM), which may be important for preventing renal fibrosis." (PMID 30466397, 2018). "IMN is often accompanied by renal fibrosis, and we found that the expression of MMP-14 increased significantly in IMN, but no obvious changes were found in MMP-2 and MMP-9." (PMID 34819020, 2021).